IFT74 (intraflagellar transport 74)
Description:
Component of the intraflagellar transport (IFT) complex B: together with IFT81, forms a tubulin-binding module that specifically mediates transport of tubulin within the cilium. Binds beta-tubulin via its basic region. Required for ciliogenesis. Essential for flagellogenesis during spermatogenesis.
Synonyms: CMG-1; CCDC2; CMG1; FLJ22621; BBS22; JBTS40; SPGF58
Tractability: PROTAC: ubiquitination databases record sites on it; its protein half-life has been measured.
Gene: Protein-coding gene on chromosome 9 (26,947,039 to 27,066,134, forward strand). Ensembl gene ENSG00000096872.
Subcellular location: Cell projection, cilium; Cytoplasmic vesicle; Cell projection, cilium, flagellum; Cytoplasmic vesicle, secretory vesicle, acrosome
Subcellular location (Human Protein Atlas): Basal body; Centriolar satellite; Golgi apparatus; Cytosol
Pathways (Reactome):
Organelle biogenesis and maintenance: Intraflagellar transport
Gene Ontology:
Molecular function: beta-tubulin binding; protein binding; chromatin binding
Biological process: cilium assembly; intraciliary transport involved in cilium assembly; intraciliary anterograde transport; intraciliary transport
Cellular component: centriolar satellite; ciliary basal body; cytoplasmic vesicle; Golgi apparatus; intraciliary transport particle A; intraciliary transport particle B; ciliary tip; cilium; motile cilium; acrosomal vesicle; centrosome; nucleus
Genetic constraint (gnomAD): Loss-of-function variants: 23 observed, 21.59 expected, observed/expected ratio (o/e) 1.07, 90% interval 0.76 to 1.51. The upper end of that interval is the gene's LOEUF score, 1.51, which puts it in group 6 of 6, group 1 being the genes least tolerant of losing a copy. Missense variants: 241 observed, 206.77 expected, observed/expected ratio (o/e) 1.17, 90% interval 1.05 to 1.3. Synonymous variants: 68 observed, 70.5 expected, observed/expected ratio (o/e) 0.96, 90% interval 0.79 to 1.18.
Gene-disease validity (ClinGen):
ClinGen rates the evidence that IFT74 causes each of these diseases.
ciliopathy-IFT74 (autosomal recessive): Definitive. Any ciliopathy caused by variants in the IFT74 gene.
Homologues: Orthologues: chimpanzee IFT74 (99% identical), macaque IFT74 (95% identical), dog IFT74 (91% identical), pig IFT74 (90% identical), rabbit IFT74 (89% identical), rat Ift74 (88% identical), mouse Ift74 (88% identical), guinea pig IFT74 (85% identical), tropical clawed frog ift74 (69% identical), zebrafish ift74 (58% identical), Caenorhabditis elegans ift-74 (24% identical).
Diseases named in the same sentence as IFT74 in open-access papers:
IFT74 is named in the same sentence as 31 diseases in open-access papers, as found by Europe PMC text mining. Sharing a sentence is not in itself a finding about the gene and the disease. The quoted sentences say what the papers report.
Bardet-Biedl syndrome (5 papers, 2022 to 2025). A ciliopathy with multisystem involvement. "In Bardet–Biedl syndrome, TTC8, BBS9, WDPCP, and IFT27 were shared by the two pipelines, and BBS4, BBS7, BBS12, and IFT74 suffered significantly different selective pressures between TG and BG birds." (PMID 35456484, 2022).
ciliopathies (4 papers, 2021 to 2025). "Recently, IFT74 has been identified as causative for human ciliopathies, Bardet–Biedl syndrome (BBS), and Joubert syndrome (JBTS)." (PMID 34502236, 2021). "In humans, IFT74 deficiency has been implicated in several ciliopathies, including BBS and JBTS." (PMID 34502236, 2021). "The pleiotropicity of these ciliopathies may be caused by the variety of IFT74 mutations." (PMID 34502236, 2021). "The nature of this complex ciliopathy is consistent with the role of IFT74 as a component of the IFT-B adaptor complex required for ciliary trafficking in both non-motile and motile cilia." (PMID 37555648, 2023). "Furthermore, our cases show that IFT74 disease caused by exon 2 deletion can cause both non-motile and motile ciliopathy features." (PMID 37555648, 2023). "CFAP45 and PROM1 are found in both atypical and secondary ciliopathies, whereas TTC26, SCLT1, DNAJB11, DYNC2LI1, ALMS1, IFT80 and IFT74 are shared between primary and atypical ciliopathies." (PMID 37542408, 2023).
Joubert syndrome (4 papers, 2021 to 2023). Joubert syndrome (JS) is characterized by congenital malformation of the brainstem and agenesis or hypoplasia of the cerebellar vermis leading to an abnormal respiratory pattern, nystagmus, hypotonia, ataxia, and delay in achieving motor milestones. "The following diseases were found in two or more cases: Joubert syndrome (IFT74/CPLANE1, n = 2) and Noonan syndrome (PTPN11/KRAS, n = 3)." (PMID 37895220, 2023).
male infertility (3 papers, 2022 to 2023). The inability of the male to effect fertilization of an ovum after a specified period of unprotected intercourse. "Eleven human cases carrying biallelic IFT74 variants have been published to date: one ATD / SRPS case, three BBS cases, five JBTS cases, and two cases with asthenozoospermia (isolated male infertility)." (PMID 37315079, 2023). "Mutations in other IFT-B gene additional to IFT74 (IFT81, IFT20, IFT27, IFT172), and in IFT-A genes (IFT140) can cause spermatogenesis defects and male infertility in mice." (PMID 37555648, 2023). "Observing male infertility in human patients is consistent with results in mouse where targeted deletion of Ift74 in the testes results in sperm tail assembly defects and male infertility." (PMID 37315079, 2023). "Additionally, deficiency in IFT74, IFT81, IFT140, and IFT172 have been proven to be related to spermiogenesis defects and male infertility." (PMID 36321563, 2022).
Obesity (3 papers, 2021 to 2024). Accumulation of substantial excess body fat. "Reports have already shown that ANKRD12, NEXN, IFT74, and ROCK1 play an important role in adipose deposition or obesity." (PMID 38474122, 2024). "Among these genes, AHI1, AKAP9, ANKRD12, CCDC18, IFT74, NEXN, etc., have been shown to play an important role in adipose deposition or obesity." (PMID 38474122, 2024).
Anxiety (1 paper, 2023). Intense feelings of nervousness, tension, or panic often arise in response to interpersonal stresses. "The EXD3 gene score (EME = 1.65%) moderated the mediation pathway of the anxiety symptom group and the IFT74 gene score (EME = 1.52%) moderated the mediation pathway of the emotional instability symptom group." (PMID 37322117, 2023).
Bardet–Biedl syndrome type 20 (1 paper, 2021). "Pathogenic variants in IFT74 have previously been reported in Bardet–Biedl syndrome type 20 (BBS20 [MIM:617119]) in two patients without signs of skeletal dysplasia." (PMID 33875766, 2021).
emotional instability (1 paper, 2023). "Of the six gene scores associated with the emotional instability symptom group, we replicated three genes including IFT74, LDHC and TMPO." (PMID 37322117, 2023).
Jeune syndrome (1 paper, 2023). Jeune syndrome, also called asphyxiating thoracic dystrophy, is a short-rib dysplasia characterized by a narrow thorax, short limbs and radiological skeletal abnormalities including "trident" aspect of the acetabula and metaphyseal changes. "Together, these findings show that IFT74 exon 2 deletion mutations can specifically give rise to Jeune syndrome–like skeletal dysplasia with variable lethality." (PMID 37555648, 2023). "IFT74 mutations were previously reported to cause a spectrum of primary ciliopathy phenotypes characterized by skeletal involvement diagnosed variously as Bardet–Biedl, Joubert, and Jeune syndrome." (PMID 37555648, 2023). "In conclusion, this study identifies IFT74 as a PCD-related gene, also characterizing affected individuals with an exon 2 deletion as a subtype of Jeune syndrome–like skeletal dysplasia." (PMID 37555648, 2023).
pulmonary disease (1 paper, 2023). "Furthermore, the affected siblings in our family were admitted to a pulmonary clinic with novel features for IFT74 mutations of severe pulmonary disease." (PMID 37555648, 2023).
pulmonary embolism (1 paper, 2018). The obstruction of the pulmonary artery or one of its branches by an embolus, sometimes associated with infarction of the lung. "Rs193219215 on ADP ribosylation factor-like GTPase 13B (ARL13B), which interacts with Intraflagellar transport 74 (IFT74), was found in two cases with pulmonary embolism (SN3230 and SN8592)." (PMID 29368655, 2018).
Retinal dystrophy (1 paper, 2023). Retinal dystrophy is an abnormality of the retina associated with a hereditary process. "Hence, these previously reported IFT74 mutations may present distinct features from the two siblings with only a few potential clinical overlaps such as retinal dystrophy." (PMID 37555648, 2023).
cancer (1 paper, 2025). A tumor composed of atypical neoplastic, often pleomorphic cells that invade other tissues. "These modules contained several cancer regulators such as Intraflagellar Transport (IFT) complex proteins (IFT74, IFT88), BBSome complex proteins (BBS2, BBS7, BBS9, BBS12), exocyst complex components (EXOC3, EXOC4, EXOC6B, EXOC7, and EXOC8), TTC8, TTC21B, EVC, and NEK1." (PMID 40700427, 2025).
respiratory disease (1 paper, 2023). "This expands the disease spectrum linked to IFT74 mutations beyond primary ciliopathies, to include motile ciliopathy and respiratory disease, and this should be reflected in genetic screens of PCD patients in future." (PMID 37555648, 2023).
IFT74 also shares sentences with these, for which no sentence is quoted: developmental delay (3 papers); genetic disease (2); skeletal dysplasia (2); amyotrophic lateral sclerosis (1); asthenozoospermia (1); Cerebellar atrophy (1); fibrosis (1); Fronto-temporal dementia (1); hypogonadism (1); Intellectual disability (1); Noonan syndrome (1); retinal ciliopathy (1); retinal degeneration (1); Retinal dysplasia (1); retinitis pigmentosa (1); retinopathy (1); Usher syndrome (1).